MTOR (mechanistic target of rapamycin kinase)
Diseases named in the same sentence as MTOR in open-access papers (continued):
Sharing a sentence is not in itself a finding about the gene and the disease.
renal cell carcinoma (continued). "Vascular endothelial growth factor (VEGF)-mediated angiogenesis and mammalian target of rapamycin (mTOR)-mediated regulation of cell growth, cell proliferation, cellular metabolism, and angiogenesis have been identified as key factors in the development of renal cell carcinoma (RCC)." (PMID 24190702, 2014). "Numerous PI3K inhibitors have entered clinical trials, while mTOR is the target of approved drugs for metastatic renal cell carcinoma (RCC)." (PMID 21834980, 2011). "Targeted therapies for metastatic renal cell carcinoma (RCC), including mammalian target of rapamycin (mTOR) inhibitors and small-molecule multikinase inhibitors, have produced clinical effects." (PMID 21791089, 2011). "mTOR signaling is critical in the development of many tumors, including renal cell carcinoma (RCC), in which mTOR can play a specific role in the angiogenesis pathways that are frequently up-regulated." (PMID 19860903, 2009). "Temsirolimus, a novel inhibitor of the mammalian target of rapamycin (mTOR), improves overall survival and progression-free survival in patients with advanced renal cell carcinoma (RCC) compared with interferon." (PMID 18458675, 2008). "In renal cell carcinoma, TQ activates AMPK, suppresses mTOR, and increases LC3 and Beclin-1 expression, leading to autophagy, which suppresses cell migration and invasion; importantly, inhibition of autophagy reverses these anti-metastatic effects." (PMID 41303508, 2025). "In renal cell carcinoma (RCC), the mTOR pathway has been reported to regulate hypoxia-inducible factor (HIF) protein expression under specific cellular conditions." (PMID 40555721, 2025). "Aberrant signaling in the JAK/STAT, AMPK/Raptor/mTOR, PI3K/AKT/mTOR, VHL/HIF/VEGFR/mTOR, FGFR3/MYC, and Wnt/β-catenin pathways has often been observed during the progression of renal cell carcinoma and urothelial carcinoma." (PMID 41445946, 2025). "In renal cell carcinoma, overexpressed exogenous proteins can enhance epithelial–mesenchymal transition (EMT) through the mTOR signaling pathway, thereby promoting the migration and invasion capabilities of tumor cells." (PMID 40573188, 2025). "Temsirolimus, an mTOR inhibitor, obstructs mTOR signaling, consequently augmenting HIF-mediated autophagy in renal cell carcinoma at concentrations of 10–50 nM." (PMID 40004215, 2025). "In contrast, renal cell carcinoma with fibromyomatous stroma (RCC-FMS) features clear cell epithelia embedded in smooth muscle stroma and mTOR pathway alterations." (PMID 41367859, 2025). "In renal cell carcinoma, overexpression of miR-17 and miR-20a enhances cell proliferation by modulating the HIF and mTOR pathways." (PMID 41473312, 2025). "Studies indicate cancers like renal cell carcinoma (RCC) and endocrine cancers that are angiogenic tumors can be treated with mTOR-Is." (PMID 39533221, 2024). "In NSCLC, gastric cancer and renal cell carcinoma, β-Elemene significantly suppresses the activation of the PI3K/AKT/mTOR pathway, and in renal cell carcinoma, it also inhibits the MAPK/ERK pathway, thereby promoting the autophagy of cancer cells." (PMID 39584140, 2024). "METTL13 is lowly expressed in renal cell carcinoma, and knockdown of METTL13 promotes the PI3K/AKT/mTOR/HIF-1α pathway leading to migratory ability and invasiveness of renal cell carcinoma cells as well as elevated Vimentin and N-cadherin." (PMID 39289775, 2024). "Similarly, the dual inhibition of PI3K and mTOR has been effective in reducing renal cell carcinoma (RCC) proliferation and viability [1517]." (PMID 39273409, 2024). "The next step is to explore how DEPDC1 regulates the AKT/mTOR/HIF1α pathway and key glycolytic enzymes, and to verify the effects of DEPDC1 in primary drug-resistant tumor animal models of renal cell carcinoma." (PMID 39068164, 2024). "In renal cell carcinoma (RCC), POSTN emerges as a key regulator, where its knockdown significantly suppresses epithelial-mesenchymal transition (EMT) through the IKL/AKT/mTOR pathway." (PMID 38375508, 2024).
renal cell carcinoma (continued). "In conclusion, renal cell carcinoma is influenced by several signaling pathways, including PI3K/AKT/mTOR and the VHL/HIF axis." (PMID 37176098, 2023). "The Akt/tuberin/mTOR pathway regulates DNA damage and repair mechanisms, potentially exposing diabetic kidneys to RCC development of renal cell carcinoma." (PMID 38028209, 2023). "Although the mTOR and VEGFR pathways dominate in the management of renal cancer, the combination of VEGFR and mTOR inhibitors with ICI and geodetics improved the prognosis of patients with renal cell carcinoma." (PMID 37305384, 2023). "A basic study found that the mTOR signaling pathway is activated by ITPKA1 and promotes renal cell carcinoma growth, migration, and invasion." (PMID 37065178, 2023). "Radiotherapy and chemotherapy have been considered ineffective for renal cell carcinoma treatment, but the introduction of TKI and mTOR targeted therapies and immunotherapies in combinations has increased the response rate of patients." (PMID 35563753, 2022). "Gene set enrichment analysis between the high- and low-risk groups revealed that tumor-related pathways, including adherens junction, ErbB, mTOR and WNT signaling pathways, renal cell carcinoma, and ubiquitin-mediated proteolysis were obviously enriched." (PMID 35371994, 2022). "Although mTOR inhibitors such as everolimus, temsirolimus and deforolimus have been approved for the treatment of RCC (renal cell carcinoma), HER2-negative breast cancer and pancreatic neuroendocrine tumor, they haven’t obtained approval for treatment in HCC patients." (PMID 35255005, 2022). "In renal cell carcinoma, PC1 favours angiogenesis and activates the phosphoinositide 3‐kinase (PI3K)/protein kinase B (AKT)/mTOR signalling cascade." (PMID 35106909, 2022). "By means of GSEA, we identified five ADAMTS14-related signaling pathways, including MTOR, PPAR, INSULIN signaling pathway, renal cell carcinoma, and renin–angiotensin system." (PMID 35572505, 2022). "In fact, two mTOR inhibitors, everolimus and temsirolimus, have been approved by the FDA for renal cell carcinoma treatment." (PMID 35579750, 2022). "Considering that autophagy inhibitors enhance the properties of currently used second-line agents, such as PD-L1 and mTOR inhibitors, TOLLIP seems to emerge not only as a prognostic factor but also as a potential therapeutic target in renal cell cancer." (PMID 36499030, 2022). "A recent study found that the ethanol extract of Patrinia scabiosaefolia induces the death of human renal cell carcinoma 786-O cells via SIRT1 and mTOR signaling-mediated metabolic disruptions." (PMID 34194607, 2021). "The drug can inhibit cellular growth and induce autophagy via the downregulation of the PI3K/AKT/mTOR pathway in the 786-O and ACHN cells of renal cell carcinoma." (PMID 33959154, 2021). "Patients in the low-risk group mainly involved in the ERBB signaling pathway, MAPK signaling pathway, MTOR signaling pathway, WNT signaling pathway, insulin signaling pathway, and renal cell carcinoma pathway, etc." (PMID 33976736, 2021). "To target mTOR signaling we used the clinically relevant mTOR inhibitor TEM, an FDA approved drug for the treatment of renal cell carcinoma." (PMID 34565342, 2021). "Renal cell carcinoma (RCC) is a fatal disease, in which the PI3K/AKT/mTOR signaling pathway serves an important role in the tumorigenesis." (PMID 32547875, 2020). "Dual mTORC1/2 inhibition suppresses Akt/mTOR signaling more effectively than selective mTORC1 inhibition and demonstrates in vivo preclinical efficacy against TFE3-fusion renal cell carcinoma." (PMID 31519159, 2019). "By using this approach, we identified the mTOR inhibitor, temsirolimus, which has been approved by the FDA for renal cell carcinoma, as a potential therapeutic agent." (PMID 30087612, 2018).
renal cell carcinoma (continued). "Chemotherapy and radiation therapy have minimal benefit in advanced renal cell carcinoma; however, survival is extended by treatment with tyrosine kinase inhibitors targeting VEGF, MTOR inhibitors, and immunotherapy." (PMID 28134850, 2017). "Two drugs that inhibit mTOR activation, RAD001 (Everolimus) and CCI-779 (Temsirolimus), are FDA approved for the treatment of advanced renal cell cancer." (PMID 26134285, 2015). "Immunotherapy with high-dose IL-2 had been the mainstay of systemic treatment for advanced renal cell carcinoma until the development of agents inhibiting the VEGF and mTOR pathways." (PMID 28326252, 2014). "Since PI3K/Akt/mTOR signaling is hyperactivated in renal cell carcinoma (RCC), inhibition of PI3K/Akt/mTOR pathway is one of target for cancer treatment." (PMID 24743574, 2014). "It induced growth arrest in renal cell carcinoma cells both in vitro and in vivo and was more effective compared to Rapamycin, a TORC1 (mTOR) inhibitor." (PMID 25221930, 2014). "Of the huge list of mTOR inhibitors developed, only Temsirolimus and Everolimus have been approved by the FDA for the treatment of advanced renal cell carcinoma." (PMID 24185040, 2013). "In the PI3K/PTEN/Akt/mTOR pathway, a synthetic lethal interaction is observed in renal cell carcinoma (RCC) cells which lack the von Hippel–Lindau tumor suppressor protein (VHL) as treatment of the cells with rapamycin, an inhibitor of mTORC1 which the tumor cells are dependent on, results in death." (PMID 23006971, 2012). "However, in a phase II trial for patients with renal cell carcinoma, it had a lower PFS than patients treated with the MTOR inhibitor everolimus." (PMID 40564038, 2025). "In several carcinoma models, including renal cell carcinoma 786-O, ACHN, and SASVO3 head-and-neck cells, TQ activates AMPK, leading to downstream mTOR inhibition and increased LC3-II/Beclin-1 expression, consistent with autophagy induction, that culminates in autophagic cell death." (PMID 41303508, 2025). "Likewise NETs share signaling pathways with renal cell carcinoma (RCC) and interestingly in RCC statins are known to inhibit the phosphorylation of AKT, mammalian target of rapamycin (mTOR), and ERK reducing cells motility." (PMID 38509261, 2024). "The only mTOR inhibitor approved for cancer treatment is temsirolimus, which was approved in 2007 for renal cell carcinoma patients, and there have been no mTOR inhibitors approved since then." (PMID 38791529, 2024). "Moreover, we further proved that TGFBI participates in the EMT process of renal cell carcinoma and affects the occurrence and development of renal cancer through the PI3K/AKT/mTOR/HIF-1α signaling pathway." (PMID 39068456, 2024). "According to the threshold of the |NES| >1.5 and nominal p-value < 0.05, we identified five signaling pathways that showed significantly different enrichment in the ADAMTS14 expression phenotype, including INSULIN, MTOR, PPAR, renal cell carcinoma, and renin–angiotensin system pathways." (PMID 35572505, 2022). "Furthermore, in renal cell carcinoma (RCC), decreased Mettl3 expression resulted in increased proliferation through induction of the PI3K/AKT/mTOR pathway." (PMID 35350378, 2022). "The genes involved in EGFR tyrosine kinase inhibitor resistance, the Ras signaling pathway, mTOR signaling pathway, PI3K-Akt signaling pathway and renal cell carcinoma are related to angiogenesis, which has also been confirmed as an important way to cope with hypoxia pressure." (PMID 36552492, 2022). "In this network, more important clustering labels were listed in 21 clusters: #1 lysosomal function, #2 Nrf2, # 5 heart failure, # 6 glia, # 7 mTOR, # 9 rapamycin, # 11 dormancy, # 13 inflammation, # 16 caenorhabditis elegans, # 17 AMPK, # 20 translocation renal cell carcinoma." (PMID 35531069, 2022).
renal cell carcinoma (continued). "Of note, whereas most experimental studies demonstrated increased anticancer efficacy of the ATP-competitive inhibitor of mTOR compared to rapalogs, a phase 2 trial in renal cell carcinoma patients reported that AZD2014, a kinase inhibitor of mTOR, was less efficient than the rapalog everolimus." (PMID 33802831, 2021). "In spite of the promising in vitro and preclinical results, dual PI3K/Akt/mTOR inhibitor NVP-BEZ235, and ATP-competitive mTOR inhibitor PP242 both failed to confirm their inhibitory efficacy against renal cell carcinoma (RCC) in clinical settings." (PMID 35082669, 2021). "Although mTOR inhibitors have shown great potential as antitumor agents, and CCI-779 has been approved by the US Food and Drug Administration (FDA) as a first-line treatment for patients with advanced refractory renal cell carcinoma." (PMID 33396624, 2020). "Different approaches (WB, IF, and IHC) to identify molecules related to mTOR activity such as mTOR, p-mTOR, and its targets, p-p70S6K, p-S6Rb, and p-4E-BP1 were compared in renal cell carcinoma biopsies using different approaches in order to find the best strategy to identify mTORC1 active tumors." (PMID 30564554, 2018). "Different studies have demonstrated that mTOR inhibitors might be beneficial in the treatment of Kaposi sarcoma, recurrent skin cancer, PTLD and renal cell carcinoma." (PMID 28160552, 2017). "A recent retrospective cohort from the International Metastatic Renal Cell Carcinoma Database Consortium (IMDC) of 4800 patients from 25 centers found that 6 targeted therapies (4 VEGF-TKIs and 2 mTOR inhibitors) were used in at least 9% of patients in the third-line setting." (PMID 28431395, 2017). "mTOR inhibition as an anticancer strategy has been previously tested, and rapalogs (temsirolimus and everolimus) were approved by FDA for the treatment of patients with advanced renal cell carcinoma, following the positive results of phase III trials." (PMID 27274989, 2016). "The results suggest that 20 miRNAs involved in the mTOR signaling pathway, the MAPK signaling pathway, the renal cell carcinoma pathway, various cancer pathways, the VEGF signaling pathway, and the vascular smooth muscle contraction pathway play regulatory roles in hypoxia adaptation in the TP." (PMID 26571238, 2015). "In addition, mTOR inhibitors increased the expression of E-cadherin and suppressed cell motility by regulating the mTOR/HIF-2α signal pathway in human renal cell carcinoma." (PMID 25996501, 2015). "Additionally, S-palmitoylation differentially affects mTOR signaling depending on cancer type: in renal cell carcinoma, ZDHHC2 enhances AGK S-palmitoylation, leading to AKT-mTORC1 activation, whereas in BrCa, ZDHHC22 reduces mTOR stability, thereby suppressing AKT-mTOR signaling." (PMID 40335986, 2025). "Furthermore, KEGG analysis revealed that these DRFGs were mostly related to the mammalian target of rapamycin (mTOR), FOXO, and AGE-RAGE signaling pathways in diabetic complications, animal autophagy, fluid shear stress, atherosclerosis, and renal cell carcinoma." (PMID 40696618, 2025). "Furthermore, renal cell carcinoma cells in vitro with TFE3 fusions are capable of growth independent of mTOR signaling." (PMID 37041531, 2023). "The combination of anti-PD-1 or anti-PD-L1 therapy with other therapeutic modalities may be the main option to achieve this, where the combination of VEGFR or mTOR inhibitors with ICI and geotechnically improves the prognosis of patients with renal cell carcinoma." (PMID 37305384, 2023).
renal cell carcinoma (continued). "Considering that the PI3K/Akt/mTOR signaling pathway is an important regulator of cell survival and proliferation, targeting circRNAs to inhibit PI3K/Akt/mTOR pathway may be an effective way to treat renal cell carcinoma." (PMID 35223991, 2022). "For patients with metastatic renal cell carcinoma (RCC), immunotherapies such as interleukin-2 have been followed by therapies targeting the vascular endothelial cell growth factor (VEGF) and mTOR signalling pathways." (PMID 34885149, 2021). "These drugs have shown potential for the treatment of renal cell carcinoma, mantle cell lymphoma and neuroendocrine tumors which has fueled the development of additional classes of PI3K pathway inhibitors targeting all or specific PI3K isoforms, AKT, mTOR, or both PI3K and mTOR." (PMID 29357370, 2018). "The mTOR protein complex functions as a serine/threonine kinase that is mainly activated by the phosphatidylinositol 3-kinase (PI3K)/AKT signaling pathway and plays a pivotal role in control of cell cycle, proliferation and cellular survival both in normal renal tubules and in renal cell carcinoma." (PMID 26506236, 2016). "Much progress has been made in the treatment of metastatic renal cell carcinoma (RCC) over the last decade, with the development of agents that block the vascular endothelial growth factor (VEGF) pathway or the mammalian target of rapamycin (mTOR) pathway." (PMID 25905038, 2015). "The multi-tyrosine kinase inhibitors sunitinib and sorafenib and the mTOR inhibitors temsirolimus/CCI-779 and everolimus/RAD001 have demonstrated efficacy for the treatment of renal cell carcinoma (RCC)." (PMID 22295124, 2012). "Specific to mTOR, rapamycin and its rapalogs temsirolimus (CCI779, Wyeth), everolimus (RAD001, Novartis), and ridaforolimus (AP23573/MK-8669, ARIAD-Merck) are known to be effective against renal cell carcinoma, and are being investigated for the treatment of other malignancies." (PMID 22680924, 2012). "Adiponectin, via AdipoR1, inhibits mTOR through AMPK activation in renal cell carcinoma (RCC), suppresses vascular endothelial growth factor (VEGF), MMP-2 and MMP-9 and increases TIMP-1 and TIMP-2 secretion, resulting in decreased growth, dissemination and angiogenesis of RCC." (PMID 37686525, 2023). "Activation of the PI3K-Akt-mTOR pathway is critical for the cellular progression of renal cell carcinoma, but many tested PI3K-mTOR kinase inhibitors failed to significantly improve the clinical symptoms of RCC patients." (PMID 35614940, 2022). "Renal cell carcinoma is not a single entity, but rather represents a constellation of tumors defined by distinct clinical and genetic signatures, with several RCC subtypes having overlapping cell biology alterations which converge on alterations to proteins e.g., mTOR and HIF." (PMID 36421797, 2022). "Another group could demonstrate a non-canonical activation of GLI1 in esophageal adenocarcinoma via TNF-α and subsequently mTOR/S6K1 while Zhou and colleagues could recently show that GLI1 and GLI2 are non-canonically activated via PI3K/AKT in human renal cell carcinoma." (PMID 28418873, 2017). "Based on these findings, it could be speculated that besides PI3K/Akt/mTOR pathway, TAK1-dependent inactivation of JNK/AP-1, and IKK signaling may be also responsible for the inhibitory effects of NVP-BEZ235 and PP242 against renal cell carcinoma but not Rapamycin." (PMID 35082669, 2021).